HDAC2 (histone deacetylase 2)
Diseases named in the same sentence as HDAC2 in open-access papers (continued):
Sharing a sentence is not in itself a finding about the gene and the disease.
neuroblastoma (16 papers, 2014 to 2025). Neuroblastoma (NB) is the most common solid, extracranial childhood tumor. "The neuroblastoma MYC oncogene MYCN recruited HDAC2 to miR-183 promoter sequences to decrease the expression of miR-183 in neuroblastoma cells." (PMID 36968022, 2023). "N-Myc has been shown to upregulate HDAC2 gene expression in neuroblastoma cells, and further recruit HDAC2 to the cyclic G2 (CCGN2) promoter, repressing CCGN2 expression and promoting cell proliferation." (PMID 33117806, 2020). "Functionally, its oncogenic potential is in part facilitated through the recruitment of HDAC2 in a forward loop to transcriptionally repress the tumor suppressive miR-183 in neuroblastoma cells." (PMID 33117806, 2020). "In this study, using microarray gene expression data, we observed that down-regulation of N-Myc or HDAC2 reactivated the expression of TP53INP1 in neuroblastoma cells." (PMID 24952595, 2014). "Herein, we uncovered a ceRNA mechanism of ARAP1-AS1-miR-2110-HDAC2 in BC cells, among which miR-2110 has been identified as an onco-suppressor in in neuroblastoma and HDAC2 is a well-recognized transcriptional co-repressor that plays a carcinogenic role in BC progression." (PMID 32110804, 2020). "HDACs could be recruited to the miRNAs promoter, for example, HDAC2 was reported in esophageal squamous cell carcinoma to suppress the expression level of miR-182 via bonding to the miR-182 promoter and also inhibit miR-133 in neuroblastoma." (PMID 35075362, 2022). "We have previously shown that the epigenetic regulation of miR-183 in neuroblastoma involves MYCN and HDAC2 in the same complex." (PMID 25853389, 2015). "We showed that HDAC2 cooperates with MYCN to suppress apoptosis mediated by miR-183, and that HDAC3 interacts with MYCN to transcriptionally repress the GRHL1 transcription factor, which exerts tumor suppressive effects in neuroblastoma." (PMID 27572323, 2016).
osteosarcoma (16 papers, 2015 to 2025). A usually aggressive malignant bone-forming mesenchymal neoplasm, predominantly affecting adolescents and young adults. "Conversely, a decrease of HDAC2 or DNMT3a expression or loss of both inhibits the formation of HDAC2/DNMT3a complex leading to transcription of genes involved in osteosarcoma stemness." (PMID 30509303, 2018). "HDAC2 acted as an oncogenic protein and a tumor-suppressor in bladder cancer and osteosarcoma cells, respectively." (PMID 32774482, 2020). "In parallel, we investigated HDAC2 expression in human osteosarcoma tissues and we found that HDAC2 was expressed in all cases and it was mainly localized in nucleus." (PMID 30509303, 2018). "Collectively, these results support a model by which the modulation of HDAC2 and DNMT3a plays a key role in generating and maintaining the cancer stem phenotype in osteosarcoma." (PMID 30509303, 2018). "Then, we identify for the first time two enzymes, HDAC2 and DNMT3a, that have a key role in maintaining stemness status of osteosarcoma cells sustaining also the tumor growth in vivo." (PMID 30509303, 2018). "Collectively, our results suggest that VPA and DAC induce an expansion of osteosarcoma CSCs, and we report for the first time that HDAC2 is a key factor regulating both CSCs phenotype and in vivo cancer growth." (PMID 30509303, 2018). "In conclusion, we have identified HDAC2 as a potential therapeutic target in human osteosarcoma treatment." (PMID 30509303, 2018). "Compared to the sham group, the SNL group had higher gene expression levels of Gadd45g (growth arrest and DNA-damage-inducible 45 gamma) and Fos (FBJ osteosarcoma oncogene), while it had lower gene expression levels of Igf1, Ccl2, Hdac2, Rtn4rl1, Nfkb2, Gpr84, Pik3cg, and Abcc8." (PMID 38790607, 2024). "Additionally, this group demonstrated that silencing HDAC2 inhibited the expression of OCN in Saos-2M osteosarcoma cell line, suggesting the importance of HDAC2 in regulating the OCN expression." (PMID 34069280, 2021). "In addition, to investigate the in vivo effects of HDAC2 downregulation on osteosarcoma tumorigenesis, we injected knocked down HDAC2-MG63 cells in mice." (PMID 30509303, 2018). "HDAC2 and DNMT3a are key enzymes in generating cancer stem phenotype in osteosarcoma; iv." (PMID 30509303, 2018). "In human osteosarcoma tissues, HDAC2 was strongly expressed in nucleus." (PMID 30509303, 2018). "HDAC2 expression on human osteosarcoma tissues was evaluated." (PMID 30509303, 2018). "These preliminary results suggest that targeting of HDAC2 could have a strong potential therapeutic implication in the treatment of human osteosarcoma." (PMID 30509303, 2018). "Finally, knockdown experiments have identified HDAC2 as an essential player in controlling osteosarcoma stemness and tumorigenesis." (PMID 30509303, 2018). "In addition, it may be hypothesized that HDAC2 could acquire the tumor-suppressive function observed in osteosarcoma." (PMID 32774482, 2020). "Moreover, in a recent paper, for the first time, HDAC2 was highlighted as a key factor regulating in vivo cancer growth and cancer stem cells (CSCs) phenotype involved in cancer initiation, progression and chemoresistance of osteosarcoma." (PMID 32039017, 2019). "Moreover, some osteosarcomas cells showed also a cytoplasmic distribution of HDAC2 reinforcing our idea that HDAC2 alteration could be an important event in tumorigenesis of osteosarcoma." (PMID 30509303, 2018). "Interestingly, an increase in sarcospheres and colonies formation rates was also detectable for HDAC2 depleted-MG63 and Saos2 cells and compared to mock cells, which further supports the idea that HDAC2 Knockdown was effective in promoting stemness of osteosarcoma cells." (PMID 30509303, 2018).
osteosarcoma (continued). "We have demonstrated that 4SC-202 inhibits osteosarcoma cell growth in vitro and in vivo, and advanced our understanding of the key roles of HDAC1, HDAC2, and HDAC3 in the biological behaviors of osteosarcoma." (PMID 34439353, 2021). "HDAC-2 is highly expressed in the more aggressive subgroups of BC and it is a key factor regulating CSC phenotype and in vivo cancer growth in osteosarcoma." (PMID 31726667, 2019). "In addition, the expression levels of several other HDAC family members, such as HDAC2, HDAC3, HDAC5, and HDAC8 were also upregulated, suggesting a potentially redundant function of HDACs in osteosarcoma." (PMID 37457661, 2023).
glioblastoma (15 papers, 2017 to 2025). The most malignant astrocytic tumor (WHO grade IV). "HDAC2 knockdown inhibits glioblastoma tumorigenesis through regulating glucose metabolism and proliferation." (PMID 41012498, 2025). "In the Shai Brain from TCGA database, HDAC2 was highly expressed in all brain tumors, including astrocytomas, oligodendrogliomas, and glioblastomas." (PMID 35260183, 2022). "Here, we showed that the combined inhibition of TRAP1 by gamitrinib and histone deacetylases (HDAC1/HDAC2) through romidepsin or panobinostat caused synergistic growth reduction of established and patient-derived xenograft (PDX) glioblastoma cells." (PMID 32664214, 2020). "The excessively reduced redox state of glioblastoma cells enhances the uptake and processing of cobalamins and promotes the activity of redox-sensitive proteins (i.e., HDAC2)." (PMID 28424758, 2017). "In addition, the knockdown of histone deacetylase 2 expressions in glioblastoma cells showed that it leads to the induction of cell death by inhibiting GLUT3." (PMID 37161350, 2023). "Beyond their involvement in microglial development, HDACs, such as HDAC2, play roles in chromatin reorganization and tumor stem cell maintenance, interacting with the TGF-β pathway to sustain tumorigenic potential, suggesting HDAC2 as a therapeutic target for primary brain tumors like glioblastoma." (PMID 40016470, 2025). "Indeed, we found a relatively high basal level of nitrosylated HDAC2 in glioblastoma stem cells cultured in the absence of NO donors, which are instead required for the generation of HDAC2-SNO in other cell systems (Salvatori L. and Illi B., unpublished)." (PMID 34947954, 2021). "As an inhibitor of HDAC1 and HDAC2, SAHA, also known as Vorinostat, has a broad spectrum of epigenetic activities through the inhibition of histone acetylation and has been used to treat several diseases including glioblastoma and non-small-cell lung carcinoma." (PMID 30453545, 2018).
acute myeloid leukemia (12 papers, 2015 to 2025). Acute myeloid leukemia (AML) is a group of neoplasms arising from precursor cells committed to the myeloid cell-line differentiation. "HDAC2 bound to the promoter sequences of miR-182 to decrease the expression of miR-182 in acute myelogenous leukemia (AML)." (PMID 36968022, 2023). "TET2 increases the activity of HDAC2, and mutations of this gene have previously been described in other neoplasms such as AML (acute myeloid leukemia) with an unfavorable prognostic value." (PMID 32933053, 2020). "It has been recently shown that the gene repressors, HDAC1 and HDAC2, became recruited to the promoter of miR-182 and represses it in acute myeloid leukemia." (PMID 29383111, 2017). "Here, we performed comparative transcriptome analyses in acute myeloid leukemia to investigate the biological implications of HDAC2 silencing versus its enzymatic inhibition using epigenetic-based drug(s)." (PMID 25473896, 2015). "Knocking down Hdac1/Hdac2 also promotes acute myeloid leukaemia and genomic instability." (PMID 29472538, 2018). "HDAC1 and HDAC2 have been proven to cooperate in regulating BRCA1 transcript and protein expression in acute myeloid leukemia (AML) cells." (PMID 29239146, 2018).
diabetes (12 papers, 2013 to 2025). "The role of HDAC2 in the development of diabetes and associated vascular complications has been well established." (PMID 34071497, 2021). "Co-immunoprecipitation of OGT showed that diabetes reduced the OGT:HDAC2 association (P < 0.05), but this difference was removed by exercise training." (PMID 23835259, 2013). "We show that exercise increases total protein O-GlcNAcylation in the type 2 diabetic db+/db+ mouse heart, and that exercise and diabetes have reciprocal effects on the association of HDAC1 and HDAC2 with fetal gene-regulating transcription factors." (PMID 23835259, 2013). "Another study showed that an SFN-enriched diet inhibited the diabetes-induced rise in histone deacetylase 2 (HDAC2) activity which correlated with histone acetylation and the transcriptional activation of the bone morphogenetic protein (BMP)-7 promoter (related to TGF-β/Smad signaling)." (PMID 38474385, 2024). "Thus, pharmacological inhibition of HDAC2 may be a potential therapeutic approach to attenuate diabetes-provoked vascular diseases." (PMID 34071497, 2021). "Histone deacetylases HDAC1/2 interact with promoters of Nox isoforms and play a role for NOX upregulation in experimental diabetes, which was prevented by a pan-HDAC inhibitor and aggravated by histone deacetylases 2 (HDAC2) overexpression." (PMID 32408480, 2020). "Sulforaphane (SFN), an inhibitor of HDAC2, can reverse renal interstitial fibrosis induced by high glucose (HG/Pal) by inhibiting HDAC2 and reactivating the BMP-7-Smad1/5/8 pathway in the mouse streptozotocin (STZ)-induced diabetes model." (PMID 36148005, 2022). "Western blot analysis showed that HDAC protein expression of class I HDACs (1, 2 and 3) in kidney tissue remained similar in all groups at the end of study, except for HDAC2 levels which had a modest, but significant increase in DM rats compared to without diabetes controls." (PMID 27901066, 2016).
bladder cancer (11 papers, 2011 to 2025). "In contrast, miR-489-3p regulates LDHA and PKM2 in pancreatic cancer29DLX1 in prostate cancer30SIX1 in melanoma31and HDAC2 in bladder cancer to inhibit tumor growth." (PMID 40858914, 2025). "Collectively, these results demonstrate that HDAC2-mediated delactylation at the K17 site of DHX15 promotes bladder cancer progression, at least in part, by modulating the alternative splicing and downregulating the mature RPL9 transcript." (PMID 41408324, 2025). "Given the established role of HDACs in driving drug resistance across cancers and the status of cisplatin-based chemotherapy as the first-line treatment for advanced bladder cancer (BCa), we investigated the specific involvement of HDAC2 in cisplatin resistance." (PMID 41408324, 2025). "How HDAC2 could lose its anti-oncogenic ability and then acquire pro-oncogenic potential in bladder cancer cells remains unknown." (PMID 32774482, 2020). "To validate the IHC result, we further determined expression of several HDACs, including HDAC4, HDAC1, and HDAC2, in the HTB4, HTB9, HTB2, HTB3, HTB5, HT1197 and HT1376 bladder cancer cells." (PMID 21507255, 2011). "In contrast, using the same platform, HDAC2, 3 and 8 were presented with a proclivity towards tumor-dependent augmented transcription, thus indicating the differential contribution of each HDAC enzyme to bladder cancer development." (PMID 30875794, 2019). "In the same direction, a small number of samples derived from human bladder cancers and adjacent non-malignant tissues were analyzed via a cDNA microarray technology, unveiling the differential expression and upregulation of HDAC2 gene in metastatic advanced Egyptian bladder cancer." (PMID 30875794, 2019).
heart failure (11 papers, 2013 to 2025). Inability of the heart to pump blood at an adequate rate to meet tissue metabolic requirements. "Ion channel expression and ventricular electrical remodelling of the APD are linked to the suppression of HDAC2 in the early stages of heart failure." (PMID 40660005, 2025). "In the early stages of heart failure, decreased HDAC2 expression is associated with delayed repolarisation and potassium channel, inwardly rectifying, subfamily j, member 2 and inwardly rectifying potassium channel 2.1 channel transcription." (PMID 40497340, 2025). "-Exercise-induced HDAC4 fragments protect against heart failure.-HDAC1/HDAC2 reverse diabetic heart pathology." (PMID 40822014, 2025). "HDAC2 is associated with the expression of Ca2+‐activated potassium voltage‐gated channel subfamily N (KCNN) potassium channels in patients with AF and heart failure, which promotes the occurrence of atrial arrhythmia." (PMID 40497340, 2025). "As previously demonstrated, cardiac-specific deletion of the mouse Hdac1 and Hdac2 genes evoked a strong heart failure phenotype, which is consistent with our finding." (PMID 30110327, 2018). "In this study, we demonstrated class I HDAC isoforms HDAC1 and HDAC2 are upregulated in cardiac fibroblasts as the animals progressed through heart failure." (PMID 25024745, 2014). "The chemical inhibition of Gsk3b in HDAC-2 deficient mice rendered them to become sensitive to hypertrophic stimulation; thus, HDAC2 and Gsk3b may be potential targets in heart failure." (PMID 39596076, 2024). "Moreover, in hearts with heart failure, both HDAC1 and HDAC2 showed strong expression in CFs, although HDAC2 maintained its expression in cardiomyocytes." (PMID 30791388, 2019).